PTK7 (protein tyrosine kinase 7 (inactive))
Description:
Inactive tyrosine kinase involved in the Wnt signaling pathway. Component of both the non-canonical (also known as the Wnt/planar cell polarity signaling) and the canonical Wnt signaling pathways. Functions in cell adhesion, cell migration, cell polarity, proliferation, actin cytoskeleton reorganization and apoptosis. Has a role in embryogenesis, epithelial tissue organization and angiogenesis. Does not bind ATP.
Synonyms: CCK-4; CCK4
Tractability: Small molecule: it belongs to a druggable protein family. Antibody: its Gene Ontology location is reachable by antibodies, with high confidence; UniProt predicts a signal peptide or a membrane-spanning region; the Human Protein Atlas places it where antibodies can reach. PROTAC: ubiquitination databases record sites on it; its protein half-life has been measured.
Gene: Protein-coding gene on chromosome 6 (43,076,257 to 43,161,719, forward strand). Ensembl gene ENSG00000112655.
Subcellular location: Cell membrane; Cell junction
Subcellular location (Human Protein Atlas): Cytosol; Plasma membrane; Vesicles; Predicted to be secreted
Gene Ontology:
Molecular function: ATP binding; protein binding; axon guidance receptor activity; coreceptor activity; protein kinase activity
Biological process: actin cytoskeleton organization; cell migration; cellular response to retinoic acid; positive regulation of canonical Wnt signaling pathway; positive regulation of neuron projection development; homophilic cell-cell adhesion; regulation of canonical Wnt signaling pathway; signal transduction; synapse organization; axon guidance
Cellular component: cell-cell junction; focal adhesion; plasma membrane; axon; neuronal cell body; anchoring junction; membrane
Genetic constraint (gnomAD): Loss-of-function variants: 39 observed, 120.76 expected, observed/expected ratio (o/e) 0.32, 90% interval 0.25 to 0.42. The upper end of that interval is the gene's LOEUF score, 0.42, which puts it in group 1 of 6, group 1 being the genes least tolerant of losing a copy. Missense variants: 1,169 observed, 1,469.9 expected, observed/expected ratio (o/e) 0.8, 90% interval 0.76 to 0.83. Synonymous variants: 546 observed, 579.27 expected, observed/expected ratio (o/e) 0.94, 90% interval 0.88 to 1.01.
Homologues: Orthologues: chimpanzee PTK7 (97% identical), macaque PTK7 (96% identical), pig PTK7 (94% identical), dog PTK7 (94% identical), guinea pig PTK7 (92% identical), mouse Ptk7 (92% identical), rat Ptk7 (91% identical), rabbit PTK7 (86% identical), tropical clawed frog ptk7 (63% identical), zebrafish ptk7a (60% identical), Drosophila melanogaster otk (29% identical), Drosophila melanogaster otk2 (13% identical).
Diseases named in the same sentence as PTK7 in open-access papers:
PTK7 is named in the same sentence as 103 diseases in open-access papers, as found by Europe PMC text mining. Sharing a sentence is not in itself a finding about the gene and the disease. The quoted sentences say what the papers report.
breast carcinoma (27 papers, 2014 to 2025). "Taken together, these data indicate that PTK7 expression is associated with patient outcome in subgroups of breast cancer patients." (PMID 39335176, 2024). "In a cohort of 118 breast cancer patients, high expression of PTK7 in lymph node metastases was associated with disease-free survival." (PMID 39335176, 2024). "High PTK7 mRNA expression was significantly associated with adverse survival of breast cancer patients (p < 0.001)." (PMID 39335176, 2024). "The aim of this retrospective study was to determine if PTK7 expression levels in breast tumours were associated with the clinical outcome of breast cancer patients." (PMID 39335176, 2024). "In breast cancer, several studies have confirmed that PTK7 expression in lymph node tissues is strongly associated with lymph node metastasis." (PMID 39474113, 2024). "The objective of this study was to evaluate PTK7 mRNA and protein expression in large and comprehensively annotated breast cancer cohorts to determine associations with clinicopathological criteria and patient survival." (PMID 39335176, 2024). "PTK7 protein and mRNA expression were associated with breast cancer-specific survival of patients with a poor prognostic Nottingham Prognostic Index (NPI) and a moderate prognostic NPI, respectively." (PMID 39335176, 2024). "High PTK7 mRNA protein expression was significantly associated with breast cancer-specific survival of ER-positive (p = 0.020), PgR-negative (p = 0.002), and HER2-negative patients (p < 0.001)." (PMID 39335176, 2024). "PTK7 is highly expressed in breast cancer and correlates with worse prognosis and associates with tumor metastasis and progression in TNBC." (PMID 34367983, 2021). "In breast cancer, PTK7 overexpression was found to be associated with the highly aggressive triple-negative subtype and its high expression in lymph node was associated with reduced disease-free survival." (PMID 25962058, 2015). "We explored patient subgroups to determine if PTK7 expression was associated with breast cancer-specific survival and determined that protein and mRNA expression were associated with survival of poor prognostic NPI groups and moderate prognostic NPI groups, respectively." (PMID 39335176, 2024). "Recent evidence including 79 consecutive invasive breast cancer tissues demonstrated that PTK7 expression is negatively associated with tumor grade and lymph node metastasis and may serve as a tumor suppressor in breast cancer." (PMID 34367983, 2021). "The overexpression of PTK7 in breast cancer suggests potential applications in early cancer diagnosis, especially through the use of PTK7-specific aptamers." (PMID 39936972, 2025). "Low‐dose administration of the PTK7‐targeting MedTAC (MedTACPTK7) resulted in a sustained reduction of PTK7 in breast cancer‐bearing mice, maintaining a 44% degradation rate three days post‐treatment, without significant systemic toxicity." (PMID 40305781, 2025). "In a breast cancer‐bearing mouse model, a single low dose of MedTACPTK7 (0.5 mg kg−1) reduced protein tyrosine kinase‐7 (PTK7) levels by up to 80% within 24 h, with sustained degradation of 44% at 72 h, demonstrating excellent pharmacokinetics." (PMID 40305781, 2025). "In breast cancer (BC), PTK7 expression levels are elevated, which is more pronounced in triple-negative breast cancer (TNBC)." (PMID 39474113, 2024). "In contrast, research on PTK7 in breast cancer, as a single-organ cancer, ranks fourth in terms of study numbers." (PMID 39474113, 2024). "There has been limited investigation of PTK7 in breast cancer, with studies focusing on patients with triple-negative disease." (PMID 39335176, 2024). "This study also investigated breast cancer cell lines to show that PTK7 mRNA expression was increased in ER-negative cell lines when compared to ER-positive cell lines." (PMID 39335176, 2024).
breast carcinoma (continued). "This study investigated PTK7 mRNA and protein expression in large breast cancer cohorts (n = 1980, n = 1082, and n = 1136, respectively)." (PMID 39335176, 2024). "PTK7 protein expression in breast cancer has been investigated in several small studies, although large variations in the clinical endpoints assessed result in conflicting observations." (PMID 39335176, 2024). "Cofetuzumab pelidotin (PTK7 inhibitor) enhanced anti-tumor effects of gedatolisib in phase I trials of individuals with ER− breast cancer." (PMID 37471270, 2023). "This study aimed to validate PTK7 as a target for breast cancer (BC) and investigate its oncogenic signaling mechanism." (PMID 37569547, 2023). "PTK7 has been shown to be overexpressed in a variety of cancers, including gastric, colon, esophageal, lung, prostate and breast cancer." (PMID 36431072, 2022). "The expression of PTK7 is upregulated and is associated with tumorigenicity in diverse cancers, including esophageal squamous cell carcinoma (ESCC) and breast cancer." (PMID 36293051, 2022). "Correlation of PTK7 expression with clinicopathological parameters was assessed using tissue microarray immunohistochemistry (IHC) staining in 280 patients with breast cancer." (PMID 34367983, 2021). "IHC staining showed that PTK7 was expressed both in the cytosol and the nucleus of breast cancer cells." (PMID 34367983, 2021). "To reveal the clinical relevance of PTK7 in breast cancer, in the present study, we evaluated breast cancer tissue samples from 280 human subjects and performed tissue microarray IHC staining against PTK7." (PMID 34367983, 2021). "In breast cancer cells, we observed that the kinase deletion mutant, was—like PTK7—endocytosed in the presence of Wnt." (PMID 34502237, 2021). "To further investigate function of PTK7 in EGFR-PI3K-Akt signaling pathway in breast cancer, we performed PTK7 and EGFR pair-wise gene correlation analysis using GEPIA and further confirmed EGFR expression positively correlated with PTK7 (R = 0.42, P = 2e-48)." (PMID 34367983, 2021). "PTK7 genetic alteration and expression levels were further analyzed using online database in different molecular subtypes of breast cancer." (PMID 34367983, 2021). "To further investigate the clinical relevance of PTK7, we evaluated breast cancer tissue samples from 280 human subjects and performed IHC staining against PTK7." (PMID 34367983, 2021). "Analyzing PTK7 localization in breast cancer cells, we discovered a Wnt-mediated mechanism by which PTK7 is removed from the membrane by caveolin-mediated endocytosis." (PMID 34502237, 2021). "PTK7 correlated genes in invasive breast carcinoma were analyzed using cBioPortal breast cancer datasets including 1,904 patients." (PMID 34367983, 2021). "Deletions of the chromosome arm 6p, in which the PTK7 gene is localized in humans, were reported in breast cancer and melanoma." (PMID 24618420, 2014). "PTK7 expression also modulates oncogenic signal transduction in breast cancer in vitro." (PMID 39335176, 2024). "Indeed, studies have shown that PTK7 plays crucial roles in various cancer types, such as lung cancer, breast cancer, esophageal cancer, and colorectal cancer." (PMID 39474113, 2024). "PTK7 mRNA expression was also analysed in the TCGA breast cancer patient cohort (n = 1082)." (PMID 39335176, 2024). "PTK7 is reportedly overexpressed in several solid tumour types, including breast and ovarian cancer, and evidence indicates its role in tumour progression and breast cancer cell behaviour." (PMID 39335176, 2024). "We determined that PTK7 expression was not clearly linked with survival in unselected patient cohorts; however, it was associated with breast cancer-specific survival of patients with poor and moderate Nottingham Prognostic Index values." (PMID 39335176, 2024). "Another study found that chemotherapy regimens other than anthracycline-based may benefit breast cancer patients with high LNT PTK7 expression." (PMID 39474113, 2024).
breast carcinoma (continued). "For example, in breast cancer patients not receiving chemotherapy, PTK7 mRNA expression in the primary tumor was associated with poor DFS." (PMID 39474113, 2024). "A total of 1136 breast cancer patient tumours were investigated for PTK7 expression." (PMID 39335176, 2024). "Role of PTK7 in leukemia, lung cancer, breast cancer, melanoma, and gynecologic tumors." (PMID 39474113, 2024). "Of these genes, PTK7, KLK6 and LIMCH1 have interesting links with breast cancer; PTK7 is a catalytically inactive receptor tyrosine kinase in the Wnt signalling pathway, and a PTK7 targeted antibody–drug conjugate has been shown to reduce tumour-initiating cells." (PMID 38036593, 2023). "These CAR-T cells all led to increased cytokine production and cytotoxicity to high PTK7-expressing breast cancer without causing obvious damage to normal tissue." (PMID 35935930, 2022). "The expression of PTK7 has been shown to be increased in breast cancer." (PMID 35935930, 2022). "PTK7-targeted CAR-T cells significantly prevented the growth of breast cancer." (PMID 35935930, 2022). "Co-expression analysis and gain- or loss-of-function of PTK7 in TNBC cell lines revealed that PTK7 participates in EGFR/Akt signaling regulation and associated with extracellular matrix organization and migration genes in breast cancer, including COL1A1, FN1, WNT5B, MMP11, MMP14 and SDC1." (PMID 34367983, 2021). "The function of PTK7 in breast cancer exhibits heterogeneity in multiple molecular subtypes may due to different cell context and intracellular signaling mechanisms." (PMID 34367983, 2021). "The controversy of PTK7 function in breast cancer may be due to its multiple molecular subtypes and heterogeneity." (PMID 34367983, 2021). "There was no significant associate of PTK7 expression with TNM stages from totally 280 breast cancer tissues." (PMID 34367983, 2021). "Although PTK7 plays a role in multiple cellular processes during tumor progression, the definite role of PTK7 in breast cancer progression remains unclear." (PMID 34367983, 2021). "In breast cancer cells, we recently discovered a caveolin-dependent mechanism by which PTK7 is removed from the membrane that may also be relevant in NC cells." (PMID 34502237, 2021). "Here we demonstrate that PTK7 were predominantly upregulated in breast cancer tissues." (PMID 34367983, 2021). "Moreover, PTK-7 expression was correlated with the triple-negative phenotype, further supporting its adverse impact on breast cancer behavior." (PMID 31820857, 2020). "On the contrary, the levels of PTK7 are decreased in metastatic melanoma and breast carcinoma." (PMID 24618420, 2014). "BC tissue analysis showed significantly elevated PTK7 mRNA levels, especially in refractory triple-negative breast cancer (TNBC) tissues, compared with normal controls." (PMID 37569547, 2023). "Genes identified in breast cancer included ERBB3, LIV‐1 and SLC44A4; in colorectal cancer CD71, PTK7 and SLC44A4; in lung cancer SLC44A4; in prostate cancer LIV‐1 and PSMA; and finally in stomach cancer CD71 and CD74." (PMID 37740463, 2023). "PTK7 expression in breast cancer was significantly positively correlated with COL1A1, FN1, WNT5B, MMP11, MMP14 and SDC1 in breast cancer." (PMID 34367983, 2021). "Protein tyrosine kinase-7 (PTK7) exhibits overexpression in breast cancer, with notably higher levels found in TNBC than in non-TNBC." (PMID 38948057, 2024). "In addition, PTK7 mRNA expression in the METABRIC (n = 1980) and the TCGA breast cancer cohorts (n = 1082) was evaluated." (PMID 39335176, 2024). "This study demonstrated that PTK7 mRNA expression in the METABRIC patient cohort, but not PTK7 protein expression, is associated with breast cancer-specific survival." (PMID 39335176, 2024). "In addition, PTK7 expression is correlated with higher cell proliferation, survival, migration, and invasion in ESCC cells and breast cancer cells, as well as enhanced tumor growth in mouse xenograft models using ESCC and TNBC cells." (PMID 36293051, 2022).
breast carcinoma (continued). "However, Gartner and colleagues found elevated PTK7 mRNA expression level in TNBC cell lines and PTK7 overexpression in metastatic lymph node predicts shorter disease-free survival (DFS) in breast cancer patients." (PMID 34367983, 2021). "PTK7 expression was qualified as low, medium and high according to IHC score and a follow-up analysis of patient overall survival showed that higher expression of PTK7 in TNBC breast cancer tissue correlated with a worse outcome." (PMID 34367983, 2021). "Thus, ADCs directed against SLC44A4 could potentially be evaluated in breast cancer; CD71, PTK7 and SLC44A4 in colorectal cancer; SLC44A4 in lung cancer; LIV‐1 in prostate cancer, and finally CD71 and CD74 in gastric cancer." (PMID 37740463, 2023). "Additionally, to investigate whether PTK7 levels influence cell proliferation at the microscopic level, we conducted immunostaining of MDA-MB-231 cells, representing one of the breast cancer cell lines, using an antibody against Ki-67, a well-known marker for cell proliferation." (PMID 37569547, 2023). "Analysis of The Cancer Genome Atlas (TCGA) data confirmed that PTK7 mRNA expression is significantly higher in TNBC tumor tissues compared with adjacent normal tissues and non-TNBC breast cancer subtypes." (PMID 39936972, 2025). "PTK7 expression in TNBC (MDA-MB-468, MDA-MB-436 and MDA-MB-231) and non-TNBC (MCF7 and SK-BR-3) breast cancer cell lines were examined using immunoblotting assay." (PMID 34367983, 2021). "Based on the observations of active non-canonical WNT signaling in breast cancer tissue, we compared the expression levels of the known four non-canonical WNT co-receptors ROR1, ROR2, PTK7 and RYK in normal and cancerous breast tissue using the TNMplot database." (PMID 34911552, 2021).